MMP9 (matrix metallopeptidase 9)
Diseases named in the same sentence as MMP9 in open-access papers (continued):
Sharing a sentence is not in itself a finding about the gene and the disease.
cancer (continued). "Therefore, the inhibition of MMP-2 or MMP-9-mediated migration or invasion may be a preventive method of limiting cancer metastasis." (PMID 24053256, 2013). "Thus, TNFα-induced MMP-9 expression via NF-κB is important for cancer growth and metastasis." (PMID 23997800, 2013). "Based on the broad substrates of MMP3 and MMP9, their potential effects may be involved in multiple steps of cancer progression, including cell survival, proliferation, epithelial-to-mesenchymal transition, migration, angiogenesis, immunosuppression, and metastasis." (PMID 23409137, 2013). "The observed increased secretion of EMMPRIN with the concomitant increase of MMP-9 secretion may imply a higher metastatic potential, since increased expression of these two proteins is correlated in several different cancers and is a poor prognostic indicator for patients." (PMID 23936495, 2013). "In addition, NF-κB regulates the expression of MMP-9 in various cancers." (PMID 23799155, 2013). "Thus EBV-induced MMP3 and MMP9 may work individually or cooperatively to promote cancer progression." (PMID 23409137, 2013). "To determine whether MMP-2 or MMP-9 in the astrocyte CM were involved in inducing cancer cell invasion, we IP’d MMP-2, MMP-9 or both in astrocyte CM with specific respective antibodies, and performed an invasion assay with the astrocyte CM depleted of the MMPs." (PMID 24324647, 2013). "Taken together, overexpression of basigin-2 increased the secretion of MMP-2/MMP-9 and cancer cell migration and invasion of HO-8910 cells, whereas the inhibition caused by basigin-2 siRNA affected HO-8910PM cell migration and invasion through MMP-2 and MMP-9 expression." (PMID 23566400, 2013). "Therefore, inhibition of invasion mediated by MMP-9 and u-PA may be a key feature for the prevention of cancer metastasis." (PMID 19789215, 2011). "In particular, MMP-9 plays a key role in the degradation of several components of the ECM, including type IV, V and XI collagen, gelatin and laminin, and has been found to be over-expressed in several types of cancer and to be associated with a worse prognosis." (PMID 21426571, 2011). "Therefore, the inhibition of migration or invasion mediated by MMP-2, MMP-9 or u-PA could be a way to prevent or inhibit cancer metastasis." (PMID 19789215, 2011). "We thus tested whether THL could inhibit the secretion of MMP-2, MMP-9, and uPA in cancer cells." (PMID 20429953, 2010). "Among them, MMP9, important in extracellular matrix degradation, is up-regulated in three of the seven cancers, and CD36, which may function in cell adhesion, is down-regulated in three of the seven cancers; both of these changes are consistent with a role of the gene products in metastasis." (PMID 21060876, 2010). "The induction of the expression of MMPs, including MMP-2 and MMP-9 is well demonstrated in the context of cancer metastasis and is purported to play a role in both angiogenesis and cellular invasiveness by contributing to the enhanced migratory phenotype of the cancer cell." (PMID 20051102, 2010). "Batimastat was the first MMPI to enter clinical trial for malignant tumours by inhibiting MMP‐1, MMP‐2, MMP‐7 and MMP‐9." (PMID 41546170, 2026). "Prinomastat was tested for treating advanced cancer and oesophagus cancer due to its high affinity for MMP‐2, MMP‐3, MMP‐9, MMP‐13 and MMP‐14." (PMID 41546170, 2026). "α-Humulene epoxide II exhibited antineoplastic activity, functioned as an apoptosis agonist, and inhibited cancer-related targets such as HIF1A and MMP9." (PMID 41346770, 2026). "Specifically, MMP2 and MMP9 are frequently overexpressed in aggressive tumors and play a key role in degrading the ECM, particularly the basal membrane, thus contributing to cancer metastasis." (PMID 41226554, 2025).
cancer (continued). "This inhibition was associated with a reduction in the expression of matrix metalloproteinases MMP-2 and MMP-9, and proteins related to epithelial–mesenchymal transition (EMT), indicating a broad impact on cancer cell aggressiveness." (PMID 40299445, 2025). "Here we show that MPNST cells secrete factors that lead to acquisition of M2 markers (CD206, CD163, MGL-1, MMP-9, VEGF-A, ARG and GS) by macrophages, enabling their induction of cancer cell growth and motility and of endothelial cell angiogenesis." (PMID 40877908, 2025). "It has been shown to prevent cancer cells from migrating and invading by decreasing the production of MMP-2/MMP-9, which is needed to degrade the extracellular matrix." (PMID 40667502, 2025). "Copper is a key component of several metalloenzymes, including matrix metalloproteinase 9 (MMP-9), SOD1, vascular adhesion protein-1 (VAP-1), and LOX, which are essential for cancer metastasis." (PMID 40809021, 2025). "Based on the interaction network generated through the STRING database, the functional relevance of MMP-9 and MMP-14 in cancer cell behavior was clearly demonstrated." (PMID 40867236, 2025). "Taken together, these findings suggest that the OCT4-DUSP6 axis promotes cancer cell migration and invasion by upregulating MMP-2 and MMP-9 through a Notch-dependent, MAPK-independent mechanism, highlighting its potential role in NSCLC progression." (PMID 41210685, 2025). "According to published studies, luteolin inhibits the activation of the immune system and the expression of MMP-9 and VEGF-A, which prevents cancer growth." (PMID 40427522, 2025). "In terms of angiogenesis and cancer promotion, the effect of BHT is controversial; it was recently reported to limit angiogenesis by targeting COX-2, HOXA-10, and MMP-9." (PMID 39856999, 2025). "MMP-2, MMP-9 and MMP-14 are also involved in the degradation of ECM components, permitting migration and invasion of cancer cells." (PMID 40492135, 2025). "Cancer cells rely on the overexpression of MMP2 and MMP9 to migrate from the source cells to adjacent tissues during these processes." (PMID 40136519, 2025). "apples, a southern Italian variety, were able to inhibit matrix metalloproteinases (MMP-2 and MMP-9) and EMT, down-regulate Smad signaling (crucial for cancer progression), and decrease levels of NF-κB." (PMID 39859345, 2025). "The expression of genes related to cancer progression and angiogenesis (e.g., VEGF and MMP9) decreased in a concentration‐dependent manner compared to normal cells, showing that PPE possessed a selective effect on cancer cell lines." (PMID 40200651, 2025). "Transcriptomic and proteomic analyses showed downregulation of migration- and invasion-related genes in cancer cells, and Western blot analysis confirmed reduced expression of MMP2, MMP9, and N-cadherin." (PMID 41226554, 2025). "MMP enzymes, such as MMP-2 and MMP-9, promote extracellular matrix (ECM) degradation and basement membrane, thereby facilitating metastasis during the progression of cancer." (PMID 41234632, 2025). "TAMs and TANs contribute to cancer pathogenesis by releasing MMP-9, VEGF and other specific pro-tumorigenic factors (e.g., neutrophil elastase), which further promote cancer cell invasion, angiogenesis, and metastasis." (PMID 41009634, 2025). "NF-κB regulates genes involved in cell proliferation (Cyclin D1), anti-apoptosis (e.g., survivin and the inhibitor of apoptosis protein), anti-cancer drug resistance (MDR1), cancer metastasis (e.g., COX-2 and MMP9), and immunomodulation." (PMID 40599807, 2025). "Specifically, it focuses on MMP9 and GRP78, which play pivotal roles in cancer progression, metastasis, and therapeutic resistance." (PMID 40679956, 2025). "Research has found that ginsenoside CK can effectively inhibit the expression of AKT/mTOR/p70S6K1 proteins in cancer cells, block the PI3K/AKT/mTOR signaling pathway, and reduce the expression of MMP2 and MMP9 proteases." (PMID 40422575, 2025).
cancer (continued). "The upregulation of SPARC, MMP9 and ITGA5 in OSF and OSCC indicates their role in the induction of fibrosis and progression to cancer." (PMID 39865173, 2025). "The anti-proliferative effects of C. sativa DCM are mainly attributed to the modulation of key molecular pathways, including the inhibition of SOD activity and GSH level, as well as the suppression of MMP-1, MMP-9, and TGF-β in both cancer cell lines." (PMID 41516029, 2025). "Additionally, reports indicate that MMP-9 knockdown may reduce cancer invasion and metastasis." (PMID 40869267, 2025). "The present study investigated the roles of two critical proteins, MMP9 and GRP78, in cancer progression and evaluated their potential as therapeutic targets using a multifaceted in silico approach." (PMID 40679956, 2025). "Ginsenoside Rg3 primarily inhibits cell migration by reducing the protein levels of MMPs such as MMP-2, MMP-7, and MMP-9, and by obstructing the EMT process in cancer cells." (PMID 40490812, 2025). "With respect to the diagnostic biomarkers, we detected significantly higher serum levels of CA125, HE4, IL-6, IL-8, G-CSF, SAA, MRP8/14, OPN, MMP9, and MMP2 in women with benign or malignant tumors than in healthy controls." (PMID 41149076, 2025). "MMP family members, such as MMP2, MMP8, and MMP9, have important roles in degrading the extracellular matrix (ECM), contributing to migration and metastasis formation in various cancers." (PMID 40566630, 2025). "As a transcription factor, c-Jun regulated the expressions of N-cadherin, E-cadherin, MMP2, MMP9 and TIMP2, which are involved in EMT and regulate migration and invasion of most cancers." (PMID 40149013, 2025). "As previously reported, EFEMP1 reduced the expression of MMP2 and MMP9 by regulating the activity of ERK1/2, thereby inhibiting the migration of cancer cells." (PMID 40316017, 2025). "Lactobacillus reduces the expression of matrix metalloproteinase-9 (MMP9), an enzyme that contributes to extracellular matrix degradation, cancer cell invasion, and metastasis." (PMID 40906420, 2025). "Integrin‐αvβ1 and MMP9 secreted by NETs can activate TGF‐β, and the activation of TGF‐β can lead to the development of cancer cells that are subject to EMT and chemoresistance." (PMID 40979214, 2025). "CAFs also secrete MMP-2 and MMP-9 that degrade the ECM to create gaps in the basement membrane and align fibronectin to support cancer cell invasion." (PMID 41429896, 2025). "To investigate the interaction modes and binding affinities of GC-3,5-diGA and 1,2,4,6-GA-glc with shared targets involved in cancer and oxidative stress, we conducted systematic molecular docking analyses on four target proteins: FGF2, TERT, MMP9, and ABCG2." (PMID 40363725, 2025). "The husk extract significantly decreased the levels of MMP9 and increased the tissue inhibitors of metalloproteinase-1 (TIMP-1) in both cancer cell lines." (PMID 41226554, 2025). "Neutrophils are polarized to the N2 TAN phenotype via Notch2–Jagged1 interaction of cancer cells and CAFs, accompanied by increased expression of ARG, C-C motif chemokine ligand 2 (CCL2), CXCR4 and MMP-9." (PMID 41429896, 2025). "Elevated expression of transcriptional regulator inhibitor of DNA binding 1 (ID1) promoted cancer cell‐mediated vasculogenic mimicry (VM) through regulation of pro‐angiogenic and pro‐cancerous genes (e.g. VE‐cadherin (CDH5), TIE2, MMP9, DKK1)." (PMID 40116596, 2025). "In line with this, GHRH antagonists of the MIA class have been shown to impede cancer cell migration and invasion by preserving E-cadherin expression and inhibiting MMP2 and MMP9 expression and activity." (PMID 40244089, 2025). "Research indicates that curcumin inhibits the migration and invasion of cancer cells by suppressing matrix metalloproteinases (MMP-2) and (MMP-9), which are enzymes that facilitate cancer spread by degrading the extracellular matrix." (PMID 40918117, 2025).
cancer (continued). "MMP-9, through ECM degradation, reduces cell–cell adhesion, promoting cancer cell detachment and invasion." (PMID 40284474, 2025). "The decrease in AKNA protein expression is thought to be due to AKNA being activated to eliminate cancer pathogens, leading to increased inflammation in the cancer microenvironment, EMT imbalance, elevated MMP-9, and enhanced cancer colonization." (PMID 39996799, 2025). "Increasing evidence has revealed that many factors secreted and produced by TAMs enhance cancer progression, such as EGF, PDGF, CXCL8, MMP9, and FGF2 in the TME." (PMID 40076874, 2025). "More specifically, reducing ID1 lowered cancer cell expression of endothelial cell genes (e.g. CDH5, TIE2) and production of pro‐angiogenic proteins (e.g. VEGF, CD31, MMP9 and IL‐8)." (PMID 40116596, 2025). "By specifically inhibiting NF-κB-dependent MMP-9 (matrix metalloproteinase-9) gene expression, delphinidin can function as a potential antimetastatic drug that inhibits PMA-induced cancer cell invasion." (PMID 40427522, 2025). "In response, activated astrocytes produce inflammatory cytokines, such as TNF and IL-6, which stimulate cancer cells and promote MMP-2 and MMP-9 secretion via the action of urokinase-type plasminogen activator (uPA)." (PMID 41429896, 2025). "Two enzymes among the MMPs, MMP-9 and MMP-2 (gelatinases), play a key role in several types of cancer." (PMID 40141020, 2025). "MMPs, including MMP-9 and MMP-2, play a role in cancer cell invasion, tumor growth, and the facilitation of metastasis." (PMID 40989799, 2025). "Thus, Mmp9 in neutrophils may represent a potential therapeutic target in cancer." (PMID 39425000, 2025). "We observed an increased in MMP9 level during NEC progression, and its involvement in cancer, endocrine disorder, infection, and relaxin signaling was noted." (PMID 39562369, 2025). "The expression of this ubiquitin ligase was found to be higher in cancer cells than in other cells, and the expression of MMP2 and MMP9 was also elevated." (PMID 39759114, 2025). "In cancer cells, TPA‐induced PKC‐/ERK‐/NF‐κB‐dependent MMP‐9 activation and migration were inhibited by wogonin." (PMID 41164269, 2025). "MMPs are involved in the migration or invasion process of various cell types, including VSMCs or cancer cells, and it has been reported that the expression of MMP2 and MMP9 in the extracellular matrix of blood vessels promotes the migration of VSMCs." (PMID 41008632, 2025). "The findings reveal key mechanisms that support cancer cell survival and adaptability, including FAO- and AKT-dependent migration, STAT3 activation, MMP-9-mediated invasiveness, and mitochondrial remodeling." (PMID 40485730, 2025). "Previous studies have demonstrated robust cancer-induced systemic changes, characterized by elevated inflammatory mediators such as IL-6, TNF-α, CXCL10, and MMP9." (PMID 41153795, 2025). "ZEB1, a key regulator of EMT, is activated in cancer cells by CCL18 secreted by TAMs, leading to the increased expression of genes involved in extracellular matrix degradation, such as MMP9, and promotes the recruitment of additional TAMs by inducing CCL2." (PMID 40362280, 2025). "MMP-9 degrades the extracellular matrix and releases VEGF to promote angiogenesis along with cancer cell intravasation." (PMID 40066096, 2025). "This was associated with the upregulation of ACE2 and the downregulation of pro-cancer biomarkers, including HIF-1α, MMP-9, and β-catenin." (PMID 41303321, 2025). "It disrupts metastasis by inhibiting the activity of matrix metalloproteinases (MMPs), particularly MMP-2 and MMP-9, which degrade the extracellular matrix (ECM) and allow cancer cells to invade surrounding tissues and enter the bloodstream." (PMID 39861761, 2025). "For example, the high intracellular calcium concentration resulting from TRPM5 activity enhances matrix metalloproteinase-9 (MMP-9) in tumors, which promotes ECM remodeling and contributes to cancer progression." (PMID 40507957, 2025).
cancer (continued). "Simultaneously, the serum levels of MMP-9 and SCC-Ag were significantly higher in the OSCC patients compared to the healthy subjects, particularly in advanced cancer cases." (PMID 38673838, 2024). "Many scholars have reported that the expression increase of IL-17 in the cancer tissues can improve cell proliferation resulting in cancer growth or elevating MMP2 and MMP9 production leading to NSCLC metastasis." (PMID 38560562, 2024). "The results showed that MMP2, MMP9, MMP12, and MMP16 promoter regions in KIRC samples were hypomethylated compared to non-cancer samples." (PMID 38560573, 2024). "MMP-2 and MMP-9 are two critical enzymes that mediate extracellular matrix (ECM) degradation, which is an important process that allows cancer cell invasion and metastasis." (PMID 38879516, 2024). "As demonstrated in previous studies, activated STAT3 promotes cancer cell metastasis through transcriptional activation of multiple mediators, including MMP2, MMP9 and EMT-related genes 51-53." (PMID 39113711, 2024). "All the studied genes involved in inflammation (MMP9, PTGS2, TNF-α, and IL-6R) were expressed by cancer cells." (PMID 39072314, 2024). "Even though it has been demonstrated that p17 modulates suppression of TKs5, NCK1, Rab40b, and MMP9 and reduces complex formation of FAK/Src and TKs5/NCK1 in B16-F10 cancer cells, the impact of p17 on the formation of invadopodia is not yet clear." (PMID 39066315, 2024). "This study demonstrates that GBM cells responding to TMZ exert adverse effects by promoting MMP9 activity, and we also propose a mechanism for TMZ-mediated MMP9 regulation, which certainly leads to promoted cancer metastasis from TMZ resistant recurrent GBM." (PMID 38906916, 2024). "Among MMPs, MMP-2, -7 and -9 have been reported to promote cancer cell migration and invasion, with MMP-2 and MMP-9 being especially prevalent in PCa progression." (PMID 39063105, 2024). "It fights against cancer cells through several pathways, including (a) control of MMP-2 and MMP-9 activities and (b) reduction of MMP-2 protein production in colorectal cancer cells (COLO 205)." (PMID 38672151, 2024). "At the molecular level, NDQ lowers cancer biomarkers, CEA, and HIF-1α, as well as the VEGF and MMP-9 metastatic biomarkers." (PMID 39474040, 2024). "Transcriptome analysis revealed a set of significantly differentially expressed secreted genes, including AFP, MMP9, MMP-7, and S100A9, which are known regulators of cancer progression and therapeutic targets in cancer patients." (PMID 38307859, 2024). "Among all of these, MMP2, MMP9, FN1, CD44, SERPINE1, and CAV1 are the most famous collaborators with PLAUR in the cell migration of multiple cancer types." (PMID 38396677, 2024). "Several studies have demonstrated that MMP1, MMP2, MMP9, MMP13 and MMP19 in some cancer tissues such as NSCLC or gastric cancer are all raised, and these MMP members can degrade basement membrane and open the channel for cancer’s invasion and metastasis." (PMID 38560562, 2024). "The mechanism of action against cancer cells is based on the regulation of the expression of vimentin, E-cadherin, vascular endothelial growth factor (VEGF) and matrix metalloproteinase-9 (MMP-9)." (PMID 38267965, 2024). "Emodin, another selected compound based on in silico experiments, inhibits cancer growth by suppressing the expression of MMP7, MMP9, VEGF, EMT, N-cadherin, b-catenin, and Snail based on the literature." (PMID 38918540, 2024). "PI3K/Akt can regulate the downstream of the NF-κB transcription factor to transcribe many metastasis-related genes, including the expression of MMP-9 and EMT markers, to promote the metastasis of cancer cells." (PMID 39062099, 2024). "Since tumors originating from human or mouse cancer cell lines expressed MMP-2 and MMP-9, we tested the spatial specificity of ACPP cleavage and localization in syngeneic murine tumors grown in immune-competent mice." (PMID 39683778, 2024).